NR4A1 (nuclear receptor subfamily 4 group A member 1)
Diseases named in the same sentence as NR4A1 in open-access papers (continued):
Sharing a sentence is not in itself a finding about the gene and the disease.
hepatocellular carcinoma (23 papers, 2013 to 2025). A malignant tumor that arises from hepatocytes. "In the context of mouse tumor models, NR4A1 (Nuclear Receptor 4A1) has emerged as a significant player, mediating NK-cell dysfunction in hepatocellular carcinoma through the IFNγ/p-STAT1/IRF1 pathway." (PMID 39920136, 2025). "Nr4a1 was noted to mediate NK cell dysfunction in hepatocellular carcinoma via the IFN-γ/p-STAT1/IRF1 pathway." (PMID 40083382, 2025). "Consistent with our results, Nr4a1 promotes gluconeogenesis and suppresses glycolysis by attenuating sumoylation-regulated Pck stability in an acetylation-dependent manner in human hepatoma cell lines." (PMID 32610475, 2020). "It was noted that a number of nuclear factors, such as FXR, PPARs, RXR, PXR, HNF and NR4A1, which play critical roles in the regulation of lipid metabolism, contribute to hepatocellular carcinoma development." (PMID 31315616, 2019). "We propose that activation of NF‐κB mediates NR4A1 induction by TRAIL in TRAIL‐resistant hepatoma cells." (PMID 30821058, 2019). "Overall, these results showed that both ISG12a and its interaction partner NR4A1 are involved in TRAIL‐mediated apoptosis in hepatoma cells." (PMID 30821058, 2019). "Moreover, TRAIL treatment can induce NR4A1 expression through the activation of NF‐κB in TRAIL‐resistant Huh7 hepatoma cells." (PMID 30821058, 2019). "NR4A1 knockdown was able to overcome TRAIL resistance in hepatocellular carcinoma cells." (PMID 30821058, 2019). "In hepatocellular carcinoma, low expression of NR4A1 was observed, promoting HCC development." (PMID 36052242, 2022).
leukemia (22 papers, 2011 to 2025). A malignant (clonal) hematologic disorder, involving hematopoietic stem cells and characterized by the presence of primitive or atypical myeloid or lymphoid cells in the bone marrow and the blood. "Translocation of NR4A1 to mitochondria is related to the apoptosis of liver cancer and leukemia cells." (PMID 40746844, 2025). "An induction of pro-apoptotic genes and enhancement of apoptosis was also seen when treating leukemia and most lymphoma cells in vitro with drugs that induce the expression of NR4A1 and NR4A3." (PMID 36831639, 2023). "In AML-mesenchymal stromal cells (MSCs)-CD34+ cells co-cultured system, this a novel COX2/NR4A1/CTNNB1 axis increased leukaemia-reactive T-effector cells and rescued cellular metabolism and anti-leukaemia immunity." (PMID 36052242, 2022). "NR4A1 is widely expressed in various tissues and plays a crucial role in the regulation of cell growth, apoptosis, the immune system, and metastasis in various tumors, such as lung and liver cancers and leukemia." (PMID 40746844, 2025). "Lithium increased NR4A1 expression in leukemia cells, suggesting that lithium may promote apoptosis via NR4A1 signaling regulation." (PMID 36831437, 2023). "In contrast, based on the results of NRA41 and NR4A3 knockout studies on mice, it was shown that the dual knockdown of both NR4A1 and NR4A3 in mice resulted in the development of leukemia, and NR4A1 and NR4A3 exhibited tumor suppressor-like activities in most blood-derived tumors." (PMID 37175855, 2023). "Decreased NR4A1 and NR4A3 expression in HSCs could result in their untimely exit from quiescence into a proliferative state favorable to the accumulation of further mutations and progression to leukemia." (PMID 35496823, 2022). "While in solid tumor-derived cell lines, NR4A1 and NR4A2 expression are high, and both receptors exhibit pro-oncogenic activities, in blood-derived tumors (leukemias and lymphomas), NR4A expression, particularly of NR4A1 and NR4A3, is low." (PMID 36831639, 2023). "Remarkably, in all three patients, NR4A3 expression levels were relatively higher after the ATRA leukemia cell differentiation treatments, whereas the expression levels of NR4A1 were not consistently or overtly altered." (PMID 36040481, 2022). "NR4A1 is reported to be largely absent in leukemia and lymphoma yet highly expressed in a myriad of solid tumors, specifically in solid tumors with enhanced metabolic rate, with elevated NR4A1 expression acting as a negative prognostic marker in affected patients." (PMID 36609611, 2023).
Insulin resistance (20 papers, 2010 to 2025). Increased resistance towards insulin, that is, diminished effectiveness of insulin in reducing blood glucose levels. "In a very recent study, functional loss of NR4A1 was reported to result in exacerbated insulin resistance in both skeletal muscle and liver and to increase intramuscular and hepatic lipid content upon high-fat diet." (PMID 20525362, 2010). "Research has found that NR4A1 is an attractive target for improving insulin resistance and preventing and treating T2DM and metabolic diseases." (PMID 40951426, 2025). "NR4A1 has been shown to be induced by insulin and thiazolidinedione drugs in 3T3-L1 adipocytes, and NR4A1 gene expression is enhanced in skeletal muscles and adipose tissues in multiple rodent models of insulin resistance." (PMID 27322146, 2016). "In skeletal muscle, activated by compounds or sport, NR4A1 could promoted glycogen synthesis and participated in insulin resistance." (PMID 38441676, 2024). "NR4A1 can affect insulin resistance and downregulated intramuscular lipid content." (PMID 35681846, 2022). "Utilizing both in vitro and in vivo approaches, we found that Lcn10 deficiency promotes macrophage polarization toward a pro-inflammatory phenotype by disrupting the Nr4a1 signaling pathway, leading to exacerbated cardiac dysfunction and insulin resistance under T2D conditions." (PMID 35757735, 2022). "Up-regulates Nr4A1; improves liver steatosis, insulin resistance and inflammation; and may prevent the pathological progression of non-alcoholic fatty liver disease." (PMID 35566359, 2022). "Therefore, we investigated in a cohort of white European subjects at increased risk for type 2 diabetes whether genetic variation within the NR4A1 gene locus contributes to prediabetic phenotypes, such as insulin resistance, ectopic fat distribution, or β-cell dysfunction." (PMID 20525362, 2010). "Hepatic glucose production and liver insulin resistance are reduced significantly, and systemic glucose metabolism is altered in mice lacking NR4A1 fed a high-fat diet." (PMID 30013988, 2018).
endometriosis (19 papers, 2020 to 2025). The growth of functional endometrial tissue in anatomic sites outside the uterine body. "By targeting receptors such as PPARs, AhR, and NR4A1, flavonoids demonstrate the capacity to modulate both metabolic and inflammatory pathways, offering a multifaceted approach to managing endometriosis." (PMID 39803270, 2025). "Recent studies show that resveratrol and flavonoids such as quercetin and kaempferol bind NR4A1 and exhibit protective NR4A1-dependent inhibition of endometriosis and cancer." (PMID 40871737, 2025). "Thus, DIM-3,5 derivatives simultaneously suppress NR4A1- and NR4A2-dependent endometriosis progression effectively and represent a promising non-hormonal therapeutic strategy to replace current hormone-based treatments, that can be associated with adverse effects." (PMID 41002243, 2025).
non-small cell lung carcinoma (19 papers, 2012 to 2025). A group of at least three distinct histological types of lung cancer, including non-small cell squamous cell carcinoma, adenocarcinoma, and large cell carcinoma. "Under chronic hypoxia conditions, NR4A1 has low expression in non-small cell lung cancer (NSCLC) cells by the mediation of HIF-1α, involved in hypoxia-induced apoptosis resistance." (PMID 36052242, 2022). "Taken together, our data suggest that isoharringtonine is a potential natural product for treatment of non-small cell lung cancers, and inhibition of NR4A1 sensitizes cancer cells to anti-cancer treatment." (PMID 33172112, 2020). "NR4A1 expression has been previously reported to be upregulated in non-small-cell lung carcinoma tissues compared to that in normal tissues, and high NR4A1 level has shown an oncogenic role as a prognostic marker for predicting adverse clinical outcomes in non-small-cell lung carcinoma." (PMID 34209871, 2021).
gastric cancer (18 papers, 2008 to 2025). A primary or metastatic malignant neoplasm involving the stomach. "NR4A1 expression is up-regulated in gastric cancer cells with higher NR4A1 levels correlating with stem-like properties of cells grown as tumor spheres." (PMID 29861853, 2018). "Csn-B and ethyl 2-[2,3,4-trimethoxy-6-(1-octanoyl)phenyl]acetate are known to interact with the NR4A1 LBD, and Csn-B activates NR4A1 and induces apoptosis in gastric cancer cells (64% at 15 μM after 48 h)." (PMID 29861853, 2018). "Recently, yet another way that NR4A1 can impact tumorigenesis was discovered where NR4A1 regulate the expression of stemness-related genes Oct-4 and Nanog in gastric cancers cells." (PMID 25269081, 2014).
lymphoma (17 papers, 2011 to 2025). A malignant (clonal) proliferation of B- lymphocytes or T- lymphocytes which involves the lymph nodes, bone marrow and/or extranodal sites. "For example, low NR4A1 expression in aggressive lymphoma was associated with poor overall survival, and enforced expression of NR4A1 induced apoptosis and suppressed xenograft tumor growth." (PMID 33172112, 2020). "Gene expression analysis of primary and engrafted lymphomas revealed that Nr4a1 is specifically implicated in the regulation of Pd1-Pdl1-Pdl2 and Ctla4-CD80-CD86 axis." (PMID 31591445, 2019). "Thereby, it seems that Nr4a1 loss significantly contributes to the immune evasion of aggressive lymphomas and that it might act as a potential target for anti-lymphoma therapy." (PMID 31591445, 2019). "It was indicated that in the case of lymphomas, pharmacotherapy aimed at increasing the expression of NR4A1 and NR4A3 is justified." (PMID 35625926, 2022). "This increase in apoptosis was caused by increased pro-apoptotic proteins, TRAIL, Bim and Puma, suggesting that Nr4a1 acts as an activator on genes responsible for apoptosis in lymphoma cells." (PMID 31683815, 2019). "RNA-Seq data revealed upregulation of immune regulator genes of the B7-CD28 family in EμMyc-Nr4a1-/- lymphomas." (PMID 31591445, 2019). "In SuDHL4 lymphoma cell lines, Nr4a1 overexpression led to increased cleaved caspase 3/7 levels and Annexin V showing an increase an apoptosis." (PMID 31683815, 2019). "Nr4a1 and Nr4a3 also regulate several different types of lymphoma, including non-Hodgkin’s and B-cell." (PMID 31683815, 2019). "In order to gain insight into the influence of cytoplasmic NR4A1 on cell death, we performed an immunohistochemistry-based analysis for cleaved caspase 3 in our cohort of aggressive lymphoma patients." (PMID 30266952, 2018). "The percentage of cytoplasmic NR4A1 expressing cells significantly correlated with the number of lymphoma cells exhibiting cleaved caspase 3 (Spearman’s rho = 0.741, p < 0.001)." (PMID 30266952, 2018). "Survival analysis using cytoplasmic NR4A1 levels exhibited a lower p-value than using NR4A1 expression levels, suggesting cytoplasmic NR4A1 as a better surrogate marker in aggressive lymphomas." (PMID 30266952, 2018). "This study provides the first evidence that the subcellular localization of NR4A1 can be clearly and robustly correlated to different lymphoma subtypes and cancer-specific survival of aggressive lymphoma patients." (PMID 30266952, 2018). "This study was designed to investigate the subcellular expression pattern of NR4A1 in aggressive lymphomas." (PMID 30266952, 2018). "Even though this confirms our observation, data on the clinico-pathological relevance of intracellular localization (cytoplasmic and nuclear) of NR4A1 in tumours and especially in lymphomas are scarce." (PMID 30266952, 2018). "Here again, expression of cFOS, MXD1, JUNB, cJUN, and DUSP1 was significantly higher (3.7 fold, 7.1 fold, 3.1 fold, 3.4 fold and 9.1 fold, respectively) in lymphomas with high cytoplasmic NR4A1 content (p < 0.036)." (PMID 30266952, 2018). "Some lymphomas have a decrease in NR4A1 expression, and overexpression of NR4A1 in certain lymphoma cells induces apoptosis and inhibits the growth of these cell-derived tumors in mice." (PMID 28903348, 2017). "For example, in lymphoma, overexpression of NR4A1 could induce apoptosis and then reduce the tumor growth." (PMID 35311465, 2022). "Furthermore, we transplanted lymphoma cells of EμMyc-Nr4a1-/- and EμMyc-Nr4a1+/+ mice into immune-competent C57BL/6 mice and immune-deficient Fox-Chase-SCID beige mice." (PMID 31591445, 2019). "This shows that Nr4a1 and Nr4a3 controls induction of apoptosis in different lymphoma cells." (PMID 31683815, 2019).
lymphoma (continued). "In our lymphoma cohort, we showed that the level of cytoplasmic NR4A1 was associated with the number of lymphoma cells exhibiting a cleaved caspase 3, suggesting that NR4A1 might target the mitochondria in aggressive lymphomas and thereby induces apoptosis." (PMID 30266952, 2018). "This aligns with our results of the cleaved caspase 3 assay and provides further support for the hypothesis that cytoplasmic NR4A1 is possibly an important factor in the survival of aggressive lymphoma patients." (PMID 30266952, 2018). "To clarify whether high cytoplasmic NR4A1 levels correspond to XPO1 overexpression, we determined the relative XPO1 expression and set it in relation to the occurrence of cytoplasmic NR4A1 in our cohort of aggressive lymphomas." (PMID 30266952, 2018). "Moreover, overexpression of NR4A1 or NR4A3 in lymphoma cells induced apoptosis, supporting a tumor-suppressive function in lymphomas." (PMID 36831639, 2023). "In aggressive lymphoma, NR4A3 has powerful tumor suppressor function similar to NR4A1." (PMID 33407456, 2021). "The obtained results point to an association between activated ERK1/2 and cytoplasmic localization of NR4A1 and indicate that ERK1/2 signalling may play a role in cytoplasmic localization of NR4A1 in aggressive lymphomas." (PMID 30266952, 2018). "The nuclear orphan receptor NR4A1 functions as tumour suppressor in aggressive lymphomas by pro-apoptotic genomic and non-genomic effects." (PMID 30266952, 2018). "However, while we only detected nuclear and no cytoplasmic NR4A1 in the non-neoplastic GC-B, the percentage of aggressive lymphoma cells with NR4A1 in the cytoplasm varied between 5–80% (on average 27.1% for NGCB- and 48.5% for GCB-DLBCL, p = 0.0004)." (PMID 30266952, 2018). "However, in a study, no hypermethylation was reported in the NR4A1 and NR4A3 genes in aggressive lymphomas." (PMID 40028473, 2025).
colitis (16 papers, 2015 to 2025). Inflammation of the colon. "NR4A1 limits inflammation in models of sepsis and colitis, likely through antagonism of the NF-κB pathway." (PMID 41188240, 2025). "Administration of NDGA alleviated experimental colitis by downregulating the GSDMD/NR4A1/NLRP3 axis-mediated macrophage pyroptosis." (PMID 40596758, 2025). "Collectively, these findings indicate that NDGA ameliorates colitis development by inhibiting GSDMD/NR4A1/NLRP3-dependent inflammatory macrophage activation." (PMID 40596758, 2025). "NR4A1 inhabits pyroptosis by transcriptionally inhibiting NLRP3 and IL-1β and colocalizing with NLRP3 in trans-Golgi to alleviate pathogenic bacteria-induced colitis." (PMID 37238692, 2023). "Nur77 (also called TR3, NGFIB, or NR4A1), a member of the NR4A family of nuclear receptors, plays a crucial role in controlling inflammatory diseases, including colitis, diabetes, sepsis, and pulmonary hypertension." (PMID 32904539, 2020).
inflammatory bowel disease (14 papers, 2015 to 2025). A spectrum of small and large bowel inflammatory diseases of unknown etiology. "NR4A1 can significantly inhibit fibroblast activation to repress intestinal fibrosis during the development of inflammatory bowel disease and vocal fold fibrosis." (PMID 39736520, 2024). "For example, IER3 is known to play a role in inflammatory bowel disease and following Leishmania infection, whereas NR4A1 modulates apoptosis of monocytes." (PMID 35082159, 2022). "NR4A1 expression has been observed to be altered in various inflammatory experimental models, including inflammatory bowel disease (IBD), multiple sclerosis (MS), and rheumatoid arthritis." (PMID 38384322, 2023).
metabolic syndrome (14 papers, 2017 to 2025). A cluster of metabolic risk factors for CARDIOVASCULAR DISEASES and TYPE 2 DIABETES MELLITUS. "NR4A1 is considered a promising therapeutic target for metabolic syndromes." (PMID 36052242, 2022). "In terms of metabolism, it has been found that targeting NR4A1 can regulate glycolytic key enzymes GLUT4, HK2, and PFK in the liver and muscle cells to target metabolic syndromes." (PMID 36052242, 2022). "Fasting induces hepatic NR4A1, which may bind to the putative NBRE of the fibroblast growth factor-21 (FGF21) promoter and regulate FGF21 expression, which plays pivotal roles in the treatment of metabolic syndromes." (PMID 30013988, 2018).
myocardial infarction (14 papers, 2006 to 2025). Gross necrosis of the myocardium, as a result of interruption of the blood supply to the area, as in coronary thrombosis. "A similar phenotype was observed in mice deficient for Nr4a1, an obligate transcription factor for Ly6Clow monocytes, in a model of myocardial infarction." (PMID 33411754, 2021). "Supporting this clinical observation, gene deficiency of Serpina3c in mice, a homolog of human SERPINA4, aggravates myocardial fibrosis and promotes cardiac fibroblast proliferation after myocardial infarction (MI) via Nr4a1/ENO1/glycolysis pathway." (PMID 41561118, 2025). "NR4A1 levels in monocytes are also known to influence the outcome in models of disease e.g. myocardial infarction, neuroinflammation and intestinal disease." (PMID 34248958, 2021). "Additionally, NR4a1 has been identified as a key regulator in inhibiting cardiac fibrosis following myocardial infarction by modulating glycolysis." (PMID 38834564, 2024).
Sepsis (14 papers, 2015 to 2025). Sepsis is defined as life-threatening organ dysfunction caused by a dysregulated host response to infection. "Another Csnb analog, n-pentyl-2-(nonanoyl) phenyl acetate (PDNPA), inhibits NFkB-dependent transactivation in RAW264.7 cells by blocking interactions of NR4A1 with p38⍺ in a mouse model for sepsis." (PMID 38540704, 2024). "The activated iNKT cells predominantly skew toward Th1 type, exerting inhibitory effects on Treg cell differentiation and impairing effector function through the downregulation of Nr4a1 expression, which persists throughout the late stage of sepsis." (PMID 39720538, 2024). "Furthermore, it was observed that overexpression of the nuclear receptor 4A1 (NR4A1) in sepsis suppressed the inflammatory response." (PMID 37382273, 2023). "Nr4a1 was also found to interact with p38 in a sepsis model of LPS-induced mononuclear macrophages." (PMID 37161357, 2023). "For example, the natural product cytosporone b (Csnb) and related compounds bind NR4A1, and the different analogs exhibit structure-dependent anticancer activity, variable effects on serum glucose levels, and the inhibition of drug-induced inflammation, fibrosis, and sepsis." (PMID 38540704, 2024). "PDPNA binds NR4A1, NR4A2, and NR4A3 but inhibits sepsis only through NR4A1." (PMID 38540704, 2024). "Thus, our findings suggest that activation of iNKT cells leading to IFN-γ production can exacerbate early sepsis by inhibiting Treg cell differentiation and effector function through an IFN-γ-Nr4a1 axis." (PMID 39720538, 2024).